AKT1 (AKT serine/threonine kinase 1)
Diseases named in the same sentence as AKT1 in open-access papers (continued):
Sharing a sentence is not in itself a finding about the gene and the disease.
ovarian carcinoma (continued). "To exemplify the power of NeDRex to extract biologically meaningful pathways from starting seeds, we used the ovarian cancer (OC) associated genes from NeDRexDB (AKT1, ALPK2, CDH1, CTNNB1, EPHB1, OPCML, PIK3CA, PRKN) and constructed disease module using the MuST algorithm." (PMID 34824199, 2021). "In ovarian cancer, AKT1 is mutated and AKT2 is amplified in about 40%." (PMID 32395722, 2020). "The somatic mutation of AKT1 isoform associated with the substitution of glutamic acid by a lysine at amino acid 17 (E17K) of Akt1 have been reported in human breast, colorectal, ovarian cancers and squamous cell lung carcinoma." (PMID 26404379, 2015). "AKT1 has been associated to breast, colorectal, and ovarian cancer formation." (PMID 25569148, 2015). "Cell proliferation and EdU incorporation assays demonstrated that AKT1 overexpression promoted cell proliferation and partially reversed the cytotoxic effects of 6RK73 in ovarian cancer cells." (PMID 41584043, 2026). "SNHG17 downregulation inhibited the tumorigenesis of epithelial ovarian cancer via the regulation of miR‐485‐5p/AKT1 axis." (PMID 38680032, 2024). "Consistent with our findings, lactate production was inhibited by blocking AKT1/GSK3β (glycogen synthase kinase 3 beta) signaling in ovarian cancer cells after treatment with the VEGFR2 kinase inhibitor apatinib." (PMID 38396845, 2024). "AKT1 is a serine/threonine kinase that is frequently activated in ovarian cancer, and it is involved in promoting cell survival, proliferation, and migration." (PMID 38666020, 2024). "On the other hand, ovarian cancer in mice with knockout of the AKT1 isoform results in smaller tumors and slower tumor growth." (PMID 38836981, 2024). "In a mouse model, knockdown of Akt1 significantly inhibited ovarian cancer cell proliferation and in vivo tumor progression, whereas disruption of Akt2 increased tumor growth." (PMID 39614261, 2024). "TCP1 protein promoted the activation of PI3K/AKT1/mTORC1 signal in ovarian cancer, supposing that TCP1 played a tumor-promoting role in pancreatic cancer." (PMID 38304253, 2023). "Kaplan–Meier survival analysis spotlighted AKT1, JUN, EGFR, and VEGFA as potential diagnostic and prognostic biomarkers for ovarian cancer." (PMID 37964873, 2023). "As a tyrosine kinase inhibitor, apatinib inhibits glycolysis by suppressing the VEGFR2/AKT1/SOX5/GLUT4 signaling pathway in ovarian cancer cells." (PMID 35069931, 2022). "In epithelial ovarian cancer cells, increased let-7 miRNA abundance was identified in spheroid cells, implicating a new role for the let-7 family in AKT1-dependent metastasis." (PMID 35269443, 2022). "Further studies demonstrated that this promotion of cell motility and growth by HK2 was probably a result of it activating of Akt1 (p-Akt1) in ovarian cancer cells." (PMID 35953860, 2022). "For example, in mice, knockdown of AKT2 or AKT3 isoforms increases ovarian cancer metastasis and tumor size, while AKT1 knockdown decreased both." (PMID 35269443, 2022). "Disruption of the AKT1 signaling pathway is sufficient to inhibit the epithelial-mesenchymal transition in epithelial ovarian cancer (EOC) cells." (PMID 35269443, 2022). "HK2 was shown to promote the motility and proliferation of human ovarian cancer cells by activating Akt1/p-Akt1." (PMID 36712881, 2022). "The fact that AKT1 is activated in 40–60% of sporadic breast or ovarian cancers establishes a potential metabolic link between familial and sporadic breast and ovarian cancer." (PMID 34316706, 2021). "Other phosphosites are found in multiple cancer types; for instance, AKT1 p.T308 was seen in both breast and ovarian cancers." (PMID 33875650, 2021).
ovarian carcinoma (continued). "As an isoform of the AKT family, AKT1 is observed to be expressed unduly in a wide assortment of many human cancers including breast and ovarian cancers." (PMID 34727985, 2021). "Akt also plays an essential role as an anti-apoptotic mediator, where siRNA knockout of the Akt1 and Akt2 isoforms results in increased apoptosis and reduced proliferation in ovarian cancer." (PMID 34316328, 2021). "The AKT2 gene is often amplified in human cancers, including lung and ovarian cancers while both AKT1 and AKT2 gene amplification has been reported in breast and colorectal cancers." (PMID 34503172, 2021). "We focused on AKT1 and AKT2 isoforms, which are expressed in most tissues and have been implicated in ovarian cancer pathogenesis in multiple studies." (PMID 33488949, 2020). "We demonstrated that the depletion of ovarian cancer cell lines from pro-survival AKT1 isoform results in more increased cell death than the depletion of AKT2 isoform." (PMID 33488949, 2020). "In an ovarian cancer network, the activity of AKT1 decreases as one goes down from top to bottom of the network indicating its important regulating activity at complete network level than at a basic level." (PMID 31752757, 2019). "Taken together, these data suggested the circPLEKHM3-miR-9 axis is an important regulator in mediating the crosstalk between Wnt/β-catenin and AKT1 signaling pathways that promote the progression of ovarian cancer." (PMID 31623606, 2019). "Our data also suggested that miR-765 coordinates the formation of 3D channels-like structures through modulation of VEGFA/AKT1/SRC-α axis in SKOV3 ovarian cancer cells." (PMID 31157166, 2019). "RNA-seq analysis of circPLEKHM3 knockdown cells revealed that AKT1 activation is one of the top targeted pathways upon deletion of circPLEKHM3 in ovarian cancer cells." (PMID 31623606, 2019). "The circPLEKHM3-miR-9 axis is an important regulator in mediating the crosstalk between Wnt/β-catenin and AKT1 signaling pathways that promote the progression of ovarian cancer." (PMID 31623606, 2019). "Among the Akt isoforms, Akt1 was frequently elevated in ovarian cancer, and our representative ovarian cancer cell lines showed higher protein expression of Akt1." (PMID 29515768, 2018). "Our data suggests that Akt1 is the main isoform responsible for ovarian cancer cell proliferation and protection against apoptosis and other studies have demonstrated an important role for Akt1 in ovarian cancer cell viability." (PMID 27533079, 2016). "Akt1 inhibition, however, decreased cell viability in the murine and ovarian cancer cells at dosages as low as 0.2μM." (PMID 27533079, 2016). "Our data show that inhibition of Akt1 significantly reduced ovarian cancer cell proliferation and inhibited tumor progression in vivo." (PMID 27533079, 2016). "The present observations reveal that Akt1 sensitive up-regulation of Orai1 contributes to or even accounts for cisplatin resistance of ovary carcinoma cells." (PMID 25015419, 2014). "Invasion of ovarian cancer cells is reduced with AKT1 knockout but to a lesser extent then PIK3CA knockout." (PMID 23591839, 2013). "Increased AKT1 activity has been observed in approximately 40% of breast and ovarian cancers and >50% of prostate carcinomas." (PMID 20604938, 2010). "In this respect, data obtained in primary cells and in breast and ovarian cancer cell lines has shown that AKT1 represses BRCA1 foci formation." (PMID 21203397, 2010). "The serine/threonine kinase AKT is a downstream target of PI3K and the activity of one of its isoforms, AKT1, is elevated in ovarian carcinomas." (PMID 18208621, 2008). "To investigate whether AKT1 counteracts the suppressive effects of 6RK73, we overexpressed AKT1 in ovarian cancer cells following 6RK73 treatment." (PMID 41584043, 2026).
ovarian carcinoma (continued). "Since our initial results showed that site-specific MARylation of RACK1 controls the translation of mRNAs that are important for the survival of ovarian cancer cells (i.e., AKT1), we sought to explore the possible role of TARG1 in the regulation of translation." (PMID 39760726, 2025). "It was reported that SNHG17 silence could inhibit the tumorigenesis of epithelial ovarian cancer via the miR‐485‐5p/AKT1 axis." (PMID 38680032, 2024). "In ovarian cancer, AKT1 induces cisplatin resistance in OV2008 cells." (PMID 36620587, 2022). "For example, upregulated circ-AKT1 could promote its parental gene AKT1 (v-akt murine thymoma viral oncogene homolog 1) expression by acting as miR-942-5p molecular sponge to suppress ovarian cancer tumor cells proliferation and migration." (PMID 36091137, 2022). "Voacangine, voacristine and isovoacristine have shown cytotoxicity against ovarian cancer (A2780 cell line), according to our computational analyzes both have affinity with AKT1 and GSK3 proteins with averages of −9.3 kcal/mol, which showed PPIs associated with endometrial cancer signaling pathways." (PMID 34205626, 2021). "An analysis of the effects of individual AKT isoforms knockdown in ovarian cancer cell lines indicate that the growth suppression shown in the AKT2 KD cell lines could be attributed to the partial inhibition of AKT1 isoform by the AKT2 targeting siRNA." (PMID 33488949, 2020). "Similarly, PAWR had significant correlations with PTEN, PI3K, and AKT1, all of which are involved in ovarian cancer." (PMID 33317551, 2020). "In this study, we observed that, depending on the concentration, MK-2206 treatment could repress AKT1 phosphorylation in ovarian cancer cells." (PMID 31623606, 2019). "Finally, overall survival analysis of a cohort of ovarian cancer patients (n = 1435) indicates that high levels of VEGFA, AKT1 and SRC-α and low miR-765 expression were associated with worst patients outcome." (PMID 31157166, 2019). "The down-regulation of circPLEKHM3 could activate AKT1, and thus promote cell proliferation and migration in ovarian cancer." (PMID 31623606, 2019). "In ovarian cancer network, out of seventy leading hubs in the ovarian cancer network, we could able to explore five such KRs which are AKT1, CD44, MCAM, KRAS and EPCAM." (PMID 31752757, 2019). "Additionally, overexpression of circPLEKHM3 inactivated AKT1, while depletion of circPLEKHM3 increased moderately phosphorylation of AKT1 but had a negligible effect on total AKT1 level in ovarian cancer cells." (PMID 31623606, 2019). "Furthermore, we designed two siRNAs to knock down AKT1 in ovarian cancer cells with depletion of circPLEKHM3." (PMID 31623606, 2019). "Our findings demonstrated that circPLEKHM3 functions as a tumor suppressor in ovarian cancer cells by targeting the miR-9/BRCA1/DNAJB6/KLF4/AKT1 axis and may be used as a prognostic indicator and therapeutic target in ovarian cancer patients." (PMID 31623606, 2019). "Activation of AKT1 and its related signaling pathways is frequently observed in ovarian cancer." (PMID 31623606, 2019). "This is consistent with the abnormal activation of AKT1 frequently observed in ovarian cancer." (PMID 31623606, 2019). "The ovarian cancer network is a tightly bound network and follows certain properties: first, the network rules out centrality-lethality rule (no central control system); second, network topology obeys fractal laws; third, out of KRs AKT1 plays central role in regulating ovarian cancer system." (PMID 31752757, 2019). "AKT1 was expressed at similar levels in breast and ovarian cancer lines." (PMID 30012111, 2018). "Although the consequences of most AKT mutations have not been functionally verified, a sporadic E17K hotspot mutation in the PH domain of AKT1 has been identified in breast, colorectal and ovarian cancers that promotes constitutive AKT1 recruitment to the plasma membrane." (PMID 28082369, 2017).
ovarian carcinoma (continued). "Our study suggests that specific disruption of Akt1 may be preferable to pan-Akt inhibition for the treatment of ovarian cancer." (PMID 27533079, 2016). "The Glu17Lys mutation seen in the binding site of AKT3 in kidney cancer was also found in the pleckstrin homology domain of AKT1 in breast, colorectal and ovarian cancers, and results in the activation of AKT1, followed by downstream signaling and cell transformation." (PMID 24362839, 2014). "The combined application of cisplatin with Akt1 inhibitors or Orai1 inhibitors may thus overcome therapy resistance of ovary carcinoma." (PMID 25015419, 2014). "This study demonstrated that HK2 could induce EMT-related proteins and reduce cell cycle inhibitor by activating Akt1 in human ovarian cancer cells, subsequently enhancing cell motility and growth, suggesting that HK2 participate in the malignant process of ovarian cancer by interacting with Akt1." (PMID 35953860, 2022). "Consequently, the marginal overview of the molecular mechanism and atomic level with W80R mutation has aimed to identify hits for optimization from large data set of compounds from the PubChem database screening of flavonoids in parallel to W80R mutant protein of AKT1 targeting ovarian cancer." (PMID 34727985, 2021). "Furthermore, when AKT1 was knocked down in ovarian cancer cells with depletion of circPLEKHM3, the upregulation of Wnt/β-catenin that resulted from downregulation of circPLEKHM3 was dramatically attenuated; the cell phenotypes were also rescued by decreasing cell proliferation and migration." (PMID 31623606, 2019). "Hence, expressions of key regulators AKT1, KRAS, EPCAM and CD44 can be correlated to increasing or decreasing the risk of disease progression, so, they can be potential prognostics markers or drug targets in ovarian cancer." (PMID 31752757, 2019). "Amplification of AKT is observed in a proportion of head and neck, gastric, pancreatic and ovarian tumors, whereas a missense mutation in the pleckstrin homology domain of AKT1 has recently been described at low frequency in breast, colorectal and ovarian cancers." (PMID 21317449, 2010). "Existing literature has reported that AKT1 is the predominant isoform driving proliferation in EOC cells and is frequently activated in ovarian cancer." (PMID 41458598, 2025). "Previous studies reported that AKT1 and VEGFA have key roles to play in the pathogenesis of ovarian cancer." (PMID 38666020, 2024). "Thr21 mutation of AKT1 has also been identified in human breast, lung, and ovarian cancers, as evidenced by data from the COSMIC and Bioportal databases, thus highlighting the potential clinical significance of AKT1 T21 phosphorylation in these cancers." (PMID 38229183, 2024). "Screening ovarian cancer cell lines commercially available—e.g., OVCA429, OVCA432, OVCAR3, DOV13, and SKOV3—shows the presence of one or multiple isoforms of Akt (Akt1, 2, and 3)." (PMID 38929705, 2024). "Inhibition of AKT1 and VEGFA signaling has been shown to reduce ovarian cancer cell proliferation, angiogenesis, and tumor growth in preclinical models." (PMID 38666020, 2024). "It is noteworthy that AKT1 can degrade prelamin A (LMNA), and that LMNA is involved in ovarian cancer." (PMID 36672361, 2023). "Here, we studied the functional impact of modulating the PI3K/AKT pathway in TIL from cervical and ovarian cancer by applying PI3K and AKT inhibitors or dual KO of AKT1/2." (PMID 36028997, 2023). "We modulated the PI3K‐AKT pathway in TIL isolated from cervical and ovarian cancer by application of AKT or PI3K inhibitors or CRISPR knockout of AKT1 and/or AKT2, and characterized their effects on TIL phenotype and effector function." (PMID 36028997, 2023). "CircPLEKHM3 regulated the expression of miR-9, BRCA1, KLF4, Akt1, DNAJB6 and performed a tumor suppressive function in ovarian cancer." (PMID 38152652, 2023).
ovarian carcinoma (continued). "The positive correlation between HK2 and p-Akt1 (r = 0.4979, p = 0.0105), fibronectin (r = 0.1850, p = 0.0320) and MMP9 (r = 0.3821, p = 0.0020) in these human ovarian cancer tissues was confirmed by using Pearson correlation analysis." (PMID 35953860, 2022). "In this study, alteration of HK2 expression in human ovarian cancer cells affected the protein level of Akt1 and p-Akt1, suggesting that there should had a potential interaction relationship between HK2 and Akt1/p-Akt1 during human ovarian cancer progress." (PMID 35953860, 2022). "The expression of VEGFR2/AKT1/SOX5/GLUT4 pathway proteins was assessed using Western blotting, and glucose uptake and lactate production assays were used to detect glycolysis in ovarian cancer cells." (PMID 31325096, 2019). "Taken together, our data revealed that circPLEKHM3 inactivates the AKT1 and canonical Wnt/β-catenin signaling pathways by regulating the expression of BRCA1, DNAJB6 and KLF4 in ovarian cancer cells." (PMID 31623606, 2019). "Then we were wondering if changes in expression levels of miR-765, VEGFA, AKT1 and SRC-α have clinical implications in ovarian cancer." (PMID 31157166, 2019). "Higher expressions of AKT1 and CD44 genes in ovarian cancer patients had higher probabilities of survival than their lower expressions." (PMID 31752757, 2019). "Activation of PI3K-AKT signaling has been found to enhance GLI1 protein stability in pancreatic and ovarian cancer and in anaplastic large cell lymphoma (ALCL), where AKT1 counteracts the inhibitory effect of GSK3β on GLI1." (PMID 31244888, 2019). "Previous studies showed that AKT1 and AKT2, the target genes of PI3K, are overexpressed in breast, gastric and ovarian cancers." (PMID 29175858, 2018). "With this approach, the distinct roles of AKT1 as a growth inducer and AKT2 as a growth and invasion repressor were well defined in ovarian cancer cells, both within the tumor and the microenvironment." (PMID 28287129, 2017). "The constitutive activation in ovarian cancer is a result of amplification of pathway components like PI3K subunits (p110), AKT isoforms (AKT1, AKT2, or AKT3), or members of the mTOR complexes (RICTOR, RAPTOR)." (PMID 27090655, 2016). "With β-actin as the reference, the western blot results indicated that the protein expression of Akt1 in the OV-H1 hybrid cells was significantly weaker than that in the hESCs and OVCAR-3 ovarian cancer cells." (PMID 27377320, 2016). "Both PIK3CA, the gene encoding the catalytic subunit of PI3K, and the AKT genes are frequently amplified in HGSOC (PIK3CA: 28%, AKT1: 5%, AKT2: 8%, AKT3: 9%), indicating their oncogenic roles in ovarian cancer." (PMID 24624361, 2014). "We found that 8 of our 93 regions contained such types of genes, nine in total, including AKT1, ARNT, PMS2, and the oncogenic ubiquitin hydrolase, DUB3 for which we previously reported abnormal demethylation in our integrated study of ovarian cancer." (PMID 23293768, 2012). "In this study, we observed that 6RK73, as a potential anti-cancer agent, significantly inhibited ovarian cancer cell growth and cell cycle progression by attenuating AKT1/ Sp1/c-Myc signaling, independent of UCHL1 inactivation." (PMID 41584043, 2026).